APP (amyloid beta precursor protein)
Diseases named in the same sentence as APP in open-access papers (continued):
Sharing a sentence is not in itself a finding about the gene and the disease.
Brain atrophy (33 papers, 2009 to 2025). Partial or complete wasting (loss) of brain tissue that was once present. "The results showed that LRGT caused the marked reduction in brain atrophy in the diabetic (db/db) and the APP/PS1xdb/db mice, as well as reduced Aβ aggregates levels (p = 0.046) and tau hyperphosphorylation (p = 0.009) in the APP/PS1xdb/db mice." (PMID 38255204, 2024). "APP gencDNAs and their transcripts in the brain should be released extracellularly with apoptosis/necrosis, the cause of brain atrophy." (PMID 38066066, 2023). "Because brain atrophy is caused by necrosis/apoptosis, these reports suggest that APP gencDNA and its transcripts are released into the plasma from injured neurons, as are other cfDNA and cfRNA." (PMID 38066066, 2023). "The preclinical study of brain atrophy in AD animal models has been mainly performed in transgenic mouse lines carrying familial AD mutations (APP and/or PS1-2 genes) and developing brain amyloidosis." (PMID 20953404, 2010). "To investigate whether apoptosis might be associated with the brain atrophy observed in D257A; APP/Ld mice, we measured levels of the cleaved 17 kDa fragment of caspase-3 as a marker of capase-3 activation." (PMID 24885175, 2014). "Taken together, the cortical thinning, reduction of hippocampal area, aberrant neuronal morphology, and increased activated caspase-3 and p25 all suggest that neurodegeneration in the absence of frank neuron loss is likely to be the underlying cause of brain atrophy of the D257A; APP/Ld mice." (PMID 24885175, 2014). "While we did not detect any effects on cortical insulin or insulin-like growth factor 1 receptor m-RNA levels, LRGT significantly reduced brain atrophy in the db/db and APP/PS1xdb/db mice." (PMID 34975451, 2021). "Severe brain atrophy was detected in the db/db and APP/PS1xdb/db mice when all the groups under study were compared." (PMID 34975451, 2021). "Brain atrophy in db/db and APP/PS1xdb/db mice was improved after EMP treatment, when the hemisection and cortical areas were measured (statistical power > 0.970)." (PMID 32264944, 2020). "Interestingly, tau knockout mice develop age-dependent iron accumulation and brain atrophy, and iron retention in the primary cultured neurons is caused by decreasing surface trafficking of APP, indicating that tau-mediated iron homeostasis might be APP-dependent." (PMID 30250423, 2018). "The amyloidogenic pathway favors loss of function APP with sequential cleavage of APP by β-secretase (BACE1) resulting in neurotoxic amyloid-β (Aβ) peptides 40 and 42, the major components of cerebral amyloid plaques associated with brain atrophy found in AD." (PMID 23801940, 2013). "Bigenic and multiple transgenic mice expressing various combinations of mutant APP and mutant tau recapitulate the combined amyloid and tau-pathology of AD, but lack neurodegeneration and brain-atrophy typical for AD." (PMID 19794916, 2009). "Interestingly, we have observed tau pathology, neuronal apoptosis and necroptosis and brain atrophy, phenotypes rarely seen in other APP models." (PMID 34789895, 2022). "A 10 min cardiac arrest causes the growth of full-length amyloid precursor protein in reactive astrocytes up to 7 days after ischemia, and Aβ and C-terminus of APP only after 6 months when extensive loss of neurons and the onset of brain atrophy have been observed." (PMID 36289917, 2022). "APP+SOD vs. APP transgenic mice showed robust brain atrophy." (PMID 35203515, 2022). "Moreover, AP39 significantly inhibited brain atrophy and ameliorated the memory deficits and Aβ deposition in APP/PS1 mice." (PMID 27057285, 2016). "Measures of brain atrophy and gastrointestinal symptoms were related to changes in plasma Aβ peptide but not drug concentration, supporting a link to inhibition of γ-secretase cleavage of the APP." (PMID 26064192, 2015).
Brain atrophy (continued). "However, during the course of our study, we noticed that the brains of 12 month-old D257A; APP/Ld mice appeared smaller compared to brains of the other genotypes, suggesting brain atrophy." (PMID 24885175, 2014). "In the presence of the APP transgene, D257A mice also exhibited significant brain atrophy with apparent cortical thinning but no frank neuron loss." (PMID 24885175, 2014). "Although the underlying mechanism of brain atrophy in the D257A; APP/Ld mice is not known, it might involve Aβ42-induced mitochondrial cytochrome c release and subsequent activation of caspase-3 to trigger apoptosis." (PMID 24885175, 2014). "The FA increase in the lateral septal nuclei may be related to the complex nuclei structure or could be related to residuals of the stereotaxic normalization of the ventral ventricles which could be increased during the development of APP mice as a result of a global brain atrophy." (PMID 23840754, 2013). "Based on these data, AP39 exerts multiple protective effects in the APP/PS1 model, including the amelioration of memory deficits, the prevention of brain atrophy, and the decrease of Aβ deposition." (PMID 27057285, 2016). "Whereas neuronal loss is not observed in APP/PS1 animals, when APP/PS1 mice are crossed with db/db mice, brain atrophy is observed as the disease progresses in APP/PS1xd/db mice, making the model more complex, and better resembling actual AD pathology." (PMID 32264944, 2020). "Previous studies of APP/Ld transgenic mice show absence of substantial brain atrophy, implying that Aβ accumulation on its own does not cause significant neurodegeneration." (PMID 24885175, 2014). "Unlike in AD patients, the brains of most lines of APP transgenic mice do not exhibit significant brain atrophy." (PMID 24885175, 2014). "The data obtained in APP(xPS1) mice might thus underpin the occurrence of developmental abnormalities rather than of the true age-dependent AD-like brain atrophy." (PMID 20953404, 2010).
Hyperglycemia (31 papers, 2013 to 2025). An increased concentration of glucose in the blood. "Hyperglycemia is associated with increased amyloid precursor protein (APP), leading to an increase in Aβ peptide production and increased permeability through endothelial tight junctions." (PMID 37761009, 2023). "We and others have suggested that hyperglycemia and hyperlipidemia of prediabetes is associated with increased Aβ accumulation in APP/PS1dE9 transgenic mice." (PMID 35073330, 2022). "The current study demonstrates that chronic hyperglycemia not only increased the SP formation but also triggered tau hyperphosphorylation and synapse loss in the brain, thus potentiating the cognitive dysfunction in the Pdx1+/−/APP/PS1 mice." (PMID 27406855, 2016). "Under acute hyperglycemia, Kir6.2+/+ APP/PS1 mice released more Aβ into the hippocampal ISF compared with Kir6.2–/– APP/PS1, demonstrating a relationship between Kir6.2, ISF glucose, and ISF Aβ." (PMID 37129980, 2023). "In response to hyperglycemia, Kir6.2+/+ APP/PS1 mice also showed a 210% increase in plasma insulin compared with fasting levels (P = 0.002), while no change on plasma insulin levels was observed in Kir6.2–/– APP/PS1 mice (P = 0.8976)." (PMID 37129980, 2023). "Peripheral STZ and the resulting hyperglycaemia have been shown to increase APP protein expression in APP/PS1 mice, thus promoting Aβ generation and directly exacerbate Aβ and tau pathologies." (PMID 35128745, 2022). "Acute hyperglycaemia in APP/PS1 mice can increase Aβ production in the hippocampal interstitial fluid, and the effect is exacerbated with increased age." (PMID 35128745, 2022). "Nevertheless, previous studies have shown that the increase of MMP2 and MMP9 activities is associated with the inflammatory process and oxidative stress in APP/PS1 mice and hyperglycemia alters the PKC-β pathway, causing an increase in MMP2." (PMID 36345028, 2022). "Pdx1+/− mice (a chronic hyperglycaemia mouse model) crossed with an APP/PS1 mouse exhibited increased tau phosphorylation, increased synaptic loss in the hippocampus, increased microglial and astrocyte activation, glucose intolerance and Aβ plaque formation." (PMID 35128745, 2022). "Acute hyperglycemia induced by glucose clamps increased the levels of Aβ in the hippocampal interstitial fluid of APP/PS1dE9 transgenic mice." (PMID 35073330, 2022). "Long-term hyperglycemia and hyperlipidemia on APP/PS1dE9 transgenic mice induced by high-fat diets are associated with elevated cortical levels of Aβ and overactivated astrocytes and microglia." (PMID 35073330, 2022). "Rather than global activation, ramified microglia were detected in the remainder of the brain parenchyma of APP/PS1dE9 transgenic mice under normoglycemia or hyperglycemia." (PMID 35073330, 2022). "The transgenic expressions of APP/Tau and hyperglycemia in 3×Tg-AD mice last the depositions of Aβ/Tau, neuroinflammation and neurodegeneration." (PMID 34106880, 2021). "This situation was maintained from 14 to 26 weeks of age, and LRGT helped to increase insulin levels in the diabetic mice (db/db-LRGT and APP/PS1xb/db-LRGT) to control hyperglycemia." (PMID 34975451, 2021). "One investigation shows that hyperglycemia inhibits APP degradation and enhances Aβ production via a reduction of APP turnover rate." (PMID 33076507, 2020). "To investigate the effects of hyperglycemia on Aβ deposition in APP/PS1 mouse brains, we compared the levels of SP and AβO between the Pdx1+/−/APP/PS1 and APP/PS1 mice." (PMID 27406855, 2016). "To determine the potential effect of chronic hyperglycemia on AD-like pathophysiology, we generated an animal model by crossbreeding APP/PS1 and Pdx1+/− mice." (PMID 27406855, 2016). "Taken together, our results indicate that chronic hyperglycemia participates in enhanced Aβ deposition through increased Aβ production and suppressed Aβ clearance in Pdx1+/−/APP/PS1 mice." (PMID 27406855, 2016).
Hyperglycemia (continued). "Our data obtained from cross-mated Pdx1+/−/APP/PS1 animals clearly demonstrated the effect of chronic hyperglycemia on AD pathology." (PMID 27406855, 2016). "Quantitative analyses demonstrated that hyperglycemia significantly increased the number and size of Aβ-immunoreactive SPs in the cortex and hippocampus of the APP/PS1 mouse brains." (PMID 27406855, 2016). "APP is degraded through proteasome and lysosome pathways, and both pathways have been reported to be altered by hyperglycemia." (PMID 23894546, 2013). "First, it has been reported that proteasome and lysosome pathway are altered by hyperglycemia and APP is degraded through both pathways." (PMID 23894546, 2013). "Takeda and colleagues (2010) generated a double transgenic APP+/ob model to undertake their investigation and found that within 8 weeks, these mice displayed marked phenotypes of hyperglycaemia, hyperinsulinemia, and glucose intolerance as compared to the APP+ cohort." (PMID 39452073, 2024). "Moreover, expression of Aβ-producing enzymes typically seen in hyperglycemia-induced neurodegenerative changes, such as amyloid precursor protein (APP), decreased with UA pretreatment, further suggesting UA’s neuroprotective role." (PMID 37637627, 2023). "Taken together, we show that hyperglycemia only slightly impairs cognitive function but that RH significantly promotes the progression of AD by inhibiting TRPC6/GLUT3-mediated glucose uptake in APP/PS1-DM mice." (PMID 35077394, 2022). "Furthermroe, Xuefu Zhuyu decoction and Astragalus membranaceus-Polysaccharides, two traditional Chinese medicine used to treat metabolic syndrome ameliorate hyperglycemia and insulin resistance also attenuate microglial and astrocytic overactivation in APP/PS1dE9 transgenic mice." (PMID 35073330, 2022). "Furthermore, increased β-site amyloid precursor protein–cleaving (APP-cleaving) enzyme 1 (BACE1), APP, and β-amyloid (Aβ) are linked with vascular disease development and increased BACE1 and Aβ accompany hyperglycemia and hyperlipidemia." (PMID 32407295, 2020). "Furthermore, in comparison with HFD-fed C57 WT mice, HFD-fed APP/PS1 demonstrated aggregated hyperglycemia, hypercholesterolemia, hyperinsulinemia, and enhanced hepatic lipid deposition, accompanied by decreased GLUTs expression in liver and skeletal muscle." (PMID 33291072, 2020). "Furthermore, hyperglycemia has been shown to increase the prevalence of AD in APP/PS1 transgenic mice." (PMID 30426182, 2019). "It remains unknown whether hyperglycemia triggers altered APP processing and the subsequent development of clinical AD pathologies." (PMID 27406855, 2016). "Importantly, the Pdx1+/−/APP/PS1 mice exhibited worse hyperglycemia with age, and their serum insulin levels were significantly lower than those of the original APP/PS1 mice (p < 0.05 or p < 0.01)." (PMID 27406855, 2016). "Taken together, our data indicated that hyperglycemia could promote AD pathogenesis by inhibiting APP degradation and enhancing Aβ production." (PMID 23894546, 2013). "Using both acute and chronic paradigms, we demonstrate that Kir6.2-KATP channels are metabolic sensors that regulate hyperglycemia-dependent increases in interstitial fluid levels of Aβ, amyloidogenic processing of APP, and amyloid plaque formation, which may be dependent on lactate release." (PMID 37129980, 2023). "We show that hyperglycemia increased both neuronal silencing and hyperactivity in APP/PS1 mice but that RH only increased the fraction of hyperactive neurons in APP/PS1-DM mice; the latter observation is corroborated by greater Aβ deposition." (PMID 35077394, 2022). "The APP695 level remained markedly increased in the APP/PS1 group compared with the WT group (p < 0.01), and the increase was significantly strengthened by hyperglycemia (p < 0.05)." (PMID 27406855, 2016).
Hyperglycemia (continued). "In AD APP/PS1 transgenic mice, chronic hyperglycemia was reported to worsen the neuropathological lesion, suggesting that glycemic control may be beneficial for decreasing the incidence of AD in diabetic patients." (PMID 28489581, 2017). "Of note, our recent data also demonstrated that GSK-3β was not inhibited in Pdx1+/−/APP/PS1 mice, indicating that GSK-3β is not closely linked to chronic hyperglycemia-induced tau hyperphosphorylation." (PMID 28467789, 2017). "Furthermore, it has been reported that acute hyperglycemia increased lactate and amyloid beta in the hippocampal interstitial fluid and that suggest increased glucose metabolism regulates neuronal activity via KATP channel in APP/PS1 mice." (PMID 30563553, 2018). "In Kir6.2+/+ APP/PS1 mice, ISF lactate increased by approximately 22% ± 8.4% during hyperglycemia, while no increase in ISF lactate was observed in Kir6.2–/– APP/PS1 mice." (PMID 37129980, 2023). "Acute hyperglycemia or chronic high-sucrose diet failed to increase ISF Aβ levels and Aβ plaque burden in Kir6.2–/– APP/PS1 mice." (PMID 37129980, 2023).
Cerebral ischemia (30 papers, 2010 to 2025). Restriction of arterial blood supply to the brain associated with insufficient oxygenation to support the metabolic requirements of the tissue. "miR-130a-3p is a potential biomarker of cerebral stroke, can affect neuronal morphology through APP, and promote the repair of neurons by promoting APP expression after cerebral ischemia." (PMID 34413720, 2021). "Previous studies demonstrated that cerebral ischemia led to the accumulation of amyloid precursor protein (APP) and beta-amyloid peptides (Aβ), in addition to stimulating the expression of presenilin, a protein involved in Aβ synthesis." (PMID 32351732, 2020). "In existing rodent models of VD, it has been observed that rodent brains demonstrate AD-characteristic pathogenesis following brain ischemia, such as the upregulation of APP, cleaving of APP into amyloid product, and Tau protein hyperphosphorylation." (PMID 26557146, 2015). "Brain ischemia and hypoxia modulates amyloid precursor protein (APP) cleavage enzymes such as β-secretase and γ-secretase, thereby resulting in increased Aβ production." (PMID 25368578, 2014). "We find that both APP−/− and BACE−/− mice have a dramatically increased risk of mortality as a result of cerebral ischemia." (PMID 22912719, 2012). "Little is known about the role of APP in astrocytes during cerebral ischemia." (PMID 36289917, 2022). "Based on the research and analyses presented here, it appears that cerebral ischemia is an event that triggers the amyloidogenic processing of the APP, the products of which, in particular amyloid, are involved in the amyloidogenic phenomenon and irreversible damage to neurons post-ischemia." (PMID 35741821, 2022). "Yokukansan prevented cognitive disturbances in APP-Tg mice, mice with intracerebroventricular Aβ-injection, rats subjected to cerebrovascular ischemia or intracerebroventricular Aβ injection with ischemia/reperfusion injury, gerbils with cerebral ischemia and rats with thiamine-deficiency." (PMID 28377723, 2017). "Brain ischemia increases the expression of amyloid precursor protein (APP) mRNAs and proteins." (PMID 24179464, 2013). "Our data suggest that not only are MLR and Cav-1 essential for maintaining and stabilizing proper synaptic signaling and neuroprotection against cerebral ischemia, but they also may serve to slow the amyloidogenic process of APP seen in AD brains." (PMID 21203469, 2010). "Evidence therefore suggests that various forms of dysregulation of the APP, BACE1 and PSEN1 and PSEN2 genes are associated with individual neuronal cell responses in the CA1 and CA3 areas of the hippocampus and temporal cortex with reversible cerebral ischemia." (PMID 35741821, 2022). "The therapeutic potential of exogenous IL4 has been well documented in several CNS pathology models including models for spinal cord injury, APP/PS1 transgenic mice, cerebral ischemia as well as multiple sclerosis." (PMID 28337124, 2017).